ANXA10 (annexin A10)
Diseases named in the same sentence as ANXA10 in open-access papers (continued):
Sharing a sentence is not in itself a finding about the gene and the disease.
adenocarcinoma (6 papers, 2017 to 2022). A common cancer characterized by the presence of malignant glandular cells. "Nuclear annexin A10 staining exhibits high specificity for adenocarcinoma of the upper gastrointestinal tract and pancreatobiliary system." (PMID 35227227, 2022). "ANXA10 represents a specific marker for adenocarcinomas of the upper gastrointestinal tract and pancreaticobiliary origin." (PMID 33807999, 2021). "Our previous mass spectrometry-based proteomics study revealed that annexin A10 (ANXA10) was uniquely overexpressed in pancreatic CD24+ adenocarcinoma cells that were dissected from clinical PDAC tissues but was absent in CD24- adjacent normal cells." (PMID 28369074, 2017). "Therefore, the evaluation of the coexpression of ANXA10 and CD24 could help understand the potential role of ANXA10 during the progression of pancreatic precursor lesions to adenocarcinoma." (PMID 28369074, 2017). "Interestingly, ANXA10 has also been proposed as a useful and highly specific biomarker for adenocarcinomas of the upper gastrointestinal tract and pancreatobiliary system, and also included in a panel of biomarkers to trace the origin of adenocarcinomas with unknown primary sites." (PMID 36247003, 2022). "Interestingly, in our previous proteomics study, ANXA10 was found uniquely overexpressed in pancreatic CD24+ adenocarcinoma cells but was absent in CD24- adjacent normal cells." (PMID 28369074, 2017).
ANXA10 also shares sentences with these, for which no sentence is quoted: Barrett esophagus (3 papers); thyroid cancer (2); acute myeloid leukemia (1); benign tumours (1); bladder tumors (1); breast carcinoma (1); clear cell renal carcinoma (1); colon tumor (1); COVID-19 (1); head and neck cancer (1); lung squamous cell carcinoma (1); osteosarcoma (1); prostate adenocarcinoma (1); sessile serrated polyp (1); steatosis (1); stomach cancer (1); Ta (1).